SVIP (small VCP interacting protein)
Diseases named in the same sentence as SVIP in open-access papers (continued):
Sharing a sentence is not in itself a finding about the gene and the disease.
liver fibrosis (3 papers, 2019 to 2025). "In conclusion, the expression of SVIP is closely associated with the level of autophagy during the development of CCl4-induced hepatic fibrosis." (PMID 30683843, 2019). "Studies have reported that the expression of SVIP closely regulates the level of autophagy, especially during the development of CCl4-induced hepatic fibrosis." (PMID 40806595, 2025). "In CCL4-induced liver fibrosis, small p97/vcp-interacting protein (SVIP) activated autophagy and alleviated liver fibrosis." (PMID 38393131, 2024). "The present study aims to investigate the key role of small VCP/p97 interacting protein (SVIP) against CCl4-induced hepatic fibrosis via activating autophagy." (PMID 30683843, 2019). "The present study aimed to investigate the relationship between increased SVIP and activated autophagy during the dynamic process from steatosis to fibrosis and the role of SVIP in protecting parenchymal cell and suppressing liver fibrosis." (PMID 30683843, 2019). "Our results suggested that starvation increases the expression of SVIP together with activation of autophagy to alleviate CCl4-induced liver fibrosis in vivo." (PMID 30683843, 2019). "Next, to reveal whether SVIP involved in attenuated rat liver fibrosis, we investigated the expression of SVIP and autophagy-related proteins in these four groups." (PMID 30683843, 2019). "The current study provides insight into the biological role of SVIP and autophagy in regulating hepatic fibrosis, targeting SVIP might be a novel therapeutic strategy in the future." (PMID 30683843, 2019). "Therefore, recent results prompted us to investigate the exact mechanism of SVIP in autophagy to inhibit liver fibrosis." (PMID 30683843, 2019). "Moreover, SVIP expression, in agreement with autophagic activity and the volume of lipid droplets, first increases and then decreases during the progression of liver fibrosis with CCl4 treatment in vivo and in vivo." (PMID 30683843, 2019). "Finally, starvation keeps SVIP and autophagy at such high levels in the rat livers that markedly delays the progress of hepatic fibrosis." (PMID 30683843, 2019). "Here, in a CCl4-treatment model, liver fibrosis could be alleviated by activating autophagy or expression of SVIP." (PMID 30683843, 2019).
Obesity (2 papers, 2017 to 2025). Accumulation of substantial excess body fat. "By corollary, we propose that SVIP overexpression in the Drosophila gut suppresses obesity-related phenotypes by increasing autophagy proficiency." (PMID 39882732, 2025). "Namely, would the combination of reduced protein diets in combination with SVIP overexpression produce an additive effect in suppressing obesity-related phenotypes?" (PMID 39882732, 2025). "Our results also highlight a specific gene, SVIP, that could be targeted for anti-obesity therapeutic approaches." (PMID 39882732, 2025).
Sepsis (2 papers, 2022). Sepsis is defined as life-threatening organ dysfunction caused by a dysregulated host response to infection. "In this study, WGCNA and DiffCorr were employed to find out novel hub genes including ZNF366, ZMYND11, SVIP and UBE2H, and we proposed for the first time their causative factors during sepsis progression." (PMID 35401666, 2022).
autoimmune disease (1 paper, 2022). A disorder resulting from loss of function or tissue destruction of an organ or multiple organs, arising from humoral or cellular immune responses of the individual to their own tissue constituents. "In the case of the autoimmune diseases, the ViP/sViP signatures were induced in some, but not others." (PMID 35577777, 2022).
B cell lymphoma (1 paper, 2023). "Additionally, SVIP undergoes DNA hypermethylation also in esophageal (8 of 35; 23%) and cervical (3 of 14; 21%) cancers and hematological malignancies (22 of 154; 14%), particularly B cell lymphoma (15 of 45; 33%)." (PMID 37408196, 2023).
breast tumor (1 paper, 2023). "Strikingly, the SVIP protein level was found to be low despite increased mRNA levels in breast tumors compared to normal tissues." (PMID 37408196, 2023). "The mRNA level of SVIP was found to be significantly higher in primary breast tumors and correlated well with its promoter methylation status and genetic alterations." (PMID 37408196, 2023). "The higher mRNA expression and lower protein expression of SVIP in breast tumor tissues compared to normal tissues may indicate a different regulatory pattern for SVIP, which deserves further investigation." (PMID 37408196, 2023). "Interestingly, we found that SVIP expression is higher in primary breast tumors and lower in metastatic breast tumors compared to normal tissues." (PMID 37408196, 2023).
fronto-temporal dementia (1 paper, 2021). "We link SVIP to VCP-dependent degenerative disease through phenotypic analysis of a known human disease-causing mutation in Drosophila VCP, and we present the identification of an SVIP mutation in a human patient diagnosed with fronto-temporal dementia (FTD)." (PMID 33479240, 2021).
head and neck cancer (1 paper, 2023). A primary or metastatic malignant neoplasm affecting the head and neck. "It has been reported that SVIP undergoes DNA hypermethylation-associated silencing in some cancer cells, especially in head and neck cancer." (PMID 37408196, 2023). "In a study that aimed to identify putative genetic and epigenetic changes in the p97/VCP-mediated ERAD pathway in human tumors, SVIP promoter CpG island was found to be methylated in 50% (19 of 38) of head and neck cancer cell lines." (PMID 37408196, 2023).
head and neck squamous cell carcinoma (1 paper, 2023). A squamous cell carcinoma that arises from any of the following anatomic sites: lip and oral cavity, nasal cavity, paranasal sinuses, pharynx, larynx, and salivary glands. "On the other hand, SVIP mRNA expression was significantly decreased, especially in head and neck squamous cell carcinoma." (PMID 37408196, 2023).
hepatoma (1 paper, 2025). "Additionally, the RNAseq data also reveals that the loss of SVIP thrusts the hepatoma cells into an acute phase response (APR)-like state, with an increase in the expression of protein synthesis genes." (PMID 40806595, 2025). "For designing a knockout (KO) strategy in a rat hepatoma model, we used the rat SVIP gene according to the Genome Browser for the Rat genome from July 2014 (Rat RGSC 6.0/rn6; chromosome 1:107,368,134-107,374,302)." (PMID 40806595, 2025). "To elucidate the factors responsible for an increased intracellular retention of lipids in the SVIP KO cells, we next performed an RNA sequencing study to compare the gene expression profile of the SVIP KO and the WT hepatoma cells." (PMID 40806595, 2025). "As a result, we observed that the complete absence of SVIP protein results in enhanced retention of VLDL in the SVIP KO hepatoma cells." (PMID 40806595, 2025). "In the current study, we generated a CRISPR-Cas9-mediated SVIP-knockout rat hepatoma cell line with the goal of further understanding the functional role of SVIP in the complex process of VLDL transport and secretion." (PMID 40806595, 2025). "To further decipher the role of SVIP in these processes, we have generated a CRISPR-Cas9-mediated SVIP-knockout rat hepatoma cell line." (PMID 40806595, 2025). "We observed that complete absence of SVIP protein resulted in enhanced retention of VLDLs in the hepatoma cells." (PMID 40806595, 2025).
lung adenocarcinoma (1 paper, 2023). A carcinoma that arises from the lung and is characterized by the presence of malignant glandular epithelial cells. "Interestingly, SVIP expression was higher in renal chromophobe cell carcinoma (Renal CH) and lung adenocarcinoma (Lung AC) while lower in renal clear cell carcinoma (Renal CC), renal papillary cell carcinoma (Renal PA), and lung squamous cell carcinoma (Lung SC) than in normal tissue." (PMID 37408196, 2023).
metastatic tumors (1 paper, 2023). "However, as a subanalysis of metastatic tumors involving ER and HER2 status is not available, it is not certain that low SVIP expression in metastatic tissue is biologically relevant." (PMID 37408196, 2023).
pancreas ductal adenocarcinoma (1 paper, 2024). "Overall, the findings show the differential expression and function of p97/VCP and SVIP in pancreas ductal adenocarcinoma cells." (PMID 39473740, 2024). "Thus, we identified the cellular localization and immunoexpression of p97/VCP and SVIP in pancreas ductal adenocarcinoma cells." (PMID 39473740, 2024). "In addition, SVIP was identified in the nucleus and cytoplasm of MIA PaCa-2 and PANC-1 pancreas ductal adenocarcinoma cells." (PMID 39473740, 2024).
pancreatic cancer (1 paper, 2024). "Immunocytochemistry and immunofluorescence were performed to detect the cellular localization and presence of p97/VCP and SVIP in pancreatic cancer cells." (PMID 39473740, 2024). "In view of the potential function of the p97/VCP and SVIP genes in pancreatic cancer progression, the next step was to perform functional analyses." (PMID 39473740, 2024). "Pancreatic cancer cells were transiently transfected with SVIP siRNA (SVIPsi), p97/VCP siRNA (p97/VCPsi), and the control siRNA (Csi) to detect whether the protein expressions of SVIP and p97/VCP were influenced by these suppressions." (PMID 39473740, 2024). "Furthermore, as p97/VCP and SVIP are important regulators of proteostasis, their higher expression in pancreatic cancer compared to normal tissues indicates that p97/VCP and SVIP could have a function in pancreatic tumorigenesis." (PMID 39473740, 2024). "The probable location of p97/VCP and SVIP in pancreatic cancer cell lines is currently unknown." (PMID 39473740, 2024). "For this reason, we aimed to examine the expression of SVIP and p97/VCP on two ERAD pathway proteins and their efficacy on pancreatic cancer migration and invasion." (PMID 39473740, 2024). "The study’s objectives are to examine the expressions of SVIP and p97/VCP in two pancreatic cancer types and to show whether these proteins aid in the invasion and migration of pancreatic cancer cells." (PMID 39473740, 2024). "However, although there have been studies on p97/VCP, the function, existence, and importance of SVIP in the subtypes of pancreatic cancer have not been examined." (PMID 39473740, 2024). "The existence and function of SVIP and p97/VCP in various types of pancreatic cancer have not yet been investigated." (PMID 39473740, 2024).
steatosis (1 paper, 2019). Increased lipid within the cytoplasm of cells. "The mechanism by which SVIP protects hepatocytes may include reducing the accumulation of fatty acid and enhancing the antioxidation in the steatosis liver." (PMID 30683843, 2019).
cancer (5 papers, 2022 to 2024). A tumor composed of atypical neoplastic, often pleomorphic cells that invade other tissues. "Previously, the downregulation of SVIP in some cancers, such as head and neck tumors, was shown to be associated with hypermethylation of SVIP promoter CpG island." (PMID 37408196, 2023). "Meanwhile, this research also demonstrated that cancer cells harboring DNA methylation-associated loss of SVIP could obtain the cellular energy for their survival mainly through glucose and aerobic glycolysis, while SVIP restoration could promote the use of the homeostatic mitochondrial respiration." (PMID 36120545, 2022). "In a recent study, a tumor suppressive function of SVIP was identified, and its expression has been related to increased ER stress and suppression of cancer growth." (PMID 39473740, 2024). "First, the differential SVIP mRNA expression was observed in most human cancers through multi-omics data analysis." (PMID 37408196, 2023). "Apart from these cancer types, the SVIP promoter CpG island was most often found to be unmethylated in the other cancer types." (PMID 37408196, 2023). "SVIP has recently started to attract attention in cancer biology studies." (PMID 37408196, 2023). "SVIP exhibited tumor suppressor features and its inhibition in SVIP-hypermethylated cancer cells." (PMID 37408196, 2023). "Recent studies have suggested that SVIP may be involved in cancer progression." (PMID 37408196, 2023). "Additionally, the cancer cells were transfected with control si, p97/VCPsi, and SVIPsi RNA to detect if the protein expression of p97/VCP and SVIP were impacted in response to this silencing." (PMID 39473740, 2024).
tumor (5 papers, 2017 to 2024). "High IGFBP-2 level was related to rapid tumor growth and shorter survival time indicating low expression of SVIP and high expression of STUB1 in GBM cells." (PMID 39138166, 2024). "In vivo bioluminescence imaging was used to trace tumor progression, and xenografts with SVIP expressing GBM cells displayed a significant suppression in tumor growth, and SVIP overexpression resulted in higher survival rate and less weight loss of mice." (PMID 39138166, 2024). "In vivo experiments using a GBM xenograft model substantiated the tumor-suppressive effects of SVIP, evident by suppressed tumor growth, decreased IGFBP-2 expression, and improved survival rates." (PMID 39138166, 2024). "When the RNA-seq data of SVIP expression in normal, tumor, and metastatic breast tissues was evaluated via the TNMplot database, the analysis revealed a higher expression level of SVIP in tumor samples not only than in normal samples, but also metastatic samples." (PMID 37408196, 2023). "Mounting research studies suggested that small VCP interacting protein (SVIP), an endogenous inhibitor of ERAD, acted as a tumor feature, and its recovery after epigenetic silencing was correlated with increased ER stress and tumor growth inhibition." (PMID 36120545, 2022). "In non-tumor brain tissue, both STUB1 and SVIP were expressed in similar regions." (PMID 39138166, 2024). "Considering that previously published reports suggesting that the tumor suppressor role of SVIP and mRNA expression and survival analysis have not exhibited a consistent pattern, the analysis of SVIP protein expression was next performed." (PMID 37408196, 2023).
diseases of the immune system (1 paper, 2022). "Because all three conditions represent diseases of the immune system that share an ‘infectious trigger’, we asked if the ViP/sViP signatures are also induced in the setting of other diseases of the immune system." (PMID 35577777, 2022).
head and neck tumor (1 paper, 2023). "It has been previously reported that SVIP restoration in deficient head and neck tumor cells blocks ERAD consisting of its role as an ERAD inhibitor." (PMID 37408196, 2023).
prostate (1 paper, 2023). "Furthermore, the regulation of the levels of SVIP and ERAD components leads to enhanced ERAD proteolytic activity, which was found to be related to prostate tumorigenesis." (PMID 37408196, 2023).
SVIP also shares sentences with these, for which no sentence is quoted: acute myeloid leukemia (2 papers); Alzheimer disease (1); benign prostatic hyperplasia (1); breast invasive carcinoma (1); breast invasive ductal carcinoma (1); breast invasive lobular carcinoma (1); cholera (1); COVID-19 (1); degenerative disease (1); gastric cancer (1); hematological malignancies (1); infection (1); infectious disease (1); lung carcinoma (1); lung squamous cell carcinoma (1); renal chromophobe cell carcinoma (1); renal clear cell carcinoma (1); renal papillary cell carcinoma (1); skin cancer (1); triple-negative breast carcinoma (1); tuberculosis (1); type 2 diabetes (1); viral infection (1).